PTCH1 (patched 1)
Diseases named in the same sentence as PTCH1 in open-access papers (continued):
Sharing a sentence is not in itself a finding about the gene and the disease.
tumor (continued). "PDT-mediated cytotoxicity reduces the population of cells driven by PTCH1 and SMO mutations, leading to tumor shrinkage and resolution in many cases." (PMID 39682631, 2024). "The tumor-induced skin expressed mRNA levels of hedgehog genes Gli1, Gli2, and Ptch1 that were 8.1, 4.4, and 3.4 times higher compared to healthy skin (all genes: p < 0.001)." (PMID 38308119, 2024). "In human tumours, the Hh pathway is disrupted either through mutations of signalling proteins such as SMO, PTCH1 and SUFU or through overexpression of HH." (PMID 39234399, 2024). "The U1 r.3A>G mutations drove 5′ cryptic alternative splicing, leading to inactivation of certain tumor-suppressor genes (e.g., PTCH1)." (PMID 38730709, 2024). "What is especially interesting is the shift of PTCH1 expression, which changes from the healthy stroma to the tumor compartment, and this is matched with the stronger GLI2 staining in the tumor as well." (PMID 38731849, 2024). "Instead, loss of NHEJ function led to the suppression of MB tumorigenesis in Ptch1+/−/DNA-PKcs−/− mice through increased DSBs and apoptosis in GCPs, leading to the killing of tumor-initiating cells." (PMID 39594660, 2024). "Genomic evaluation has been performed in neoplasms from one individual with cutaneous BCC in situ and metastatic BCC; like other variants of BCC, an aberration of the PTCH1 gene was observed." (PMID 39429413, 2024). "Overexpression of Sloan–Kettering viral oncogene homolog (Ski), a protein which can function both as an oncoprotein and a tumor suppressor gene, leads to increased expression of Shh pathway components, such as Shh, Ptch-1, Smo, Gli1, and Gli2." (PMID 37815662, 2023). "Especially in Ptch1+/− mice, which develop only one tumor per individual, the incidence of R-type tumors increases, whereas that of S-type tumors decreases in a dose-dependent manner." (PMID 37117033, 2023). "Two patients received long‐term TMZ chemotherapy before surgery, and mutations in the SHh (PTCH1) and PI3K/AKT signaling pathways (AKT1, PIK3CA, PTPN11) were detected in two tumor tissues (Patients 24 and 27)." (PMID 37533228, 2023). "Among other tumor types, they develop MB with a spontaneous incidence of about 40% when the Ptch1 deletion is expressed in a C57Bl/6 background." (PMID 37175984, 2023). "To investigate the possibility that the CTD of PTCH1 plays a role in its tumour suppressor activity, we searched for the existence of CTD mutations in the Cancer Genome Atlas (TCGA) database." (PMID 36672319, 2023). "Recent studies have shown that PAMD can down-regulate the expression of Shh, Ptch1, Smo and Gli1, key loci of the Hedgehog signalling pathway, and inhibit the growth of tumour cells, thus achieving anti-tumour effects." (PMID 36985672, 2023). "For example, overexpression of Shh was observed in CD133+ cells and accelerated tumor growth while inhibition of Shh or shRNA knockdown of Shh delayed tumor growth and downregulated Ptch1 and Gli1." (PMID 37274223, 2023). "If this is the case, mutations in the CTD that jeopardize the binding of ATG101 should impair the tumour suppressor function of PTCH1." (PMID 36672319, 2023). "The inhibition resulted in decreased expression of Ptch1 and Gli1, increased level of apoptosis, and decreased tumor weight and volume." (PMID 37815662, 2023). "BCC, the most common skin cancer, is primarily driven by mutations in the PTCH1 or SMO genes, resulting in uncontrolled activation of the Hedgehog pathway and thus promoting tumor formation." (PMID 37568743, 2023).
tumor (continued). "Correspondingly, PTCH1 was uniquely expressed in csCAFs and myCAFs pointing to an interaction between classical tumor-related desmoplasia." (PMID 37633924, 2023). "BCC is characterized by dysregulated activation of the Hedgehog signaling pathway due to mutations in PTCH1 or SMO genes, leading to uncontrolled cell proliferation and tumor formation, making the pathway a target for BCC treatments." (PMID 37568743, 2023). "Patched 1 (PTCH1) is one component of hedgehog pathway, which has been correlated with tumor malignancies." (PMID 36874015, 2023). "The genomic instability resulting from ablation of these tumor suppressors drives MB development through the amplification of MYCN and PTCH2, an isoform of the frequently mutated PTCH1 of SHH MB possessing smoothened inhibitory features." (PMID 35747808, 2022). "IHH, PTCH1 and GLI1 expression levels were strongly associated with each other and with tumour proliferation in human osteosarcoma cell lines and primary tumour specimens." (PMID 36457847, 2022). "Conversely, increase in stromal pathway activity with partial loss of Ptch1 in stroma led to a decrease in stromal BMP inhibitors and decreased tumor burden." (PMID 36010600, 2022). "Our analyses showed that Ptch1 was present in primary tumor samples from the 70 ACC patients of the cohort studied." (PMID 35631574, 2022). "Targeted sequencing revealed six PTCH1 variants of interest, and two SMO variants of interest in the pre-treatment tumor." (PMID 36455049, 2022). "LncRNA LINC-PINT, as a tumor suppressor gene, targets miR-425-5p which targets Ptch1 of the Hh pathway to modulate laryngeal carcinoma cell stemness and chemoresistance." (PMID 35581586, 2022). "Noteworthy, decrease of tissue communication by ablation of one copy of Connexin 43 (Cx43) gene, reduced the bystander tumor response in the cerebellum of Ptch1+/– mice." (PMID 36001144, 2022). "BCC, the most frequent neoplasia in NBCCS, is also accompanied by secondary mutations in the wild-type PTCH1 gene." (PMID 35618979, 2022). "Upregulated expression of most KmiRNAs that regulate PTCH1 in this study suggests that suppression of PTCH1 also induces the development of BCCs and further demonstrates the function of PTCH1 as a tumor suppressor." (PMID 34395634, 2021). "Considering the difference of incidence of each tumor type in PTCH1 and SUFU PV carriers, the participants felt that screening should be adapted to the genetic background (PTCH1- or SUFU-associated GS)." (PMID 33860896, 2021). "In particular, the TERT‐mediated up‐regulation of miR500A results in the post‐transcriptional repression of PTCH1, triggering a ligand‐independent aberrant Hh signalling that significantly increases tumour cell invasiveness in a zebrafish xenograft model." (PMID 33713376, 2021). "In MB allografted mice daily treated with MEN1611 via oral gavage we observed a highly significant tumor growth inhibition relative to vehicle-treated mice, with a rescue of proliferative and anti-apoptotic phenotype of Ptch1+/−/Tis21KO MB." (PMID 34395258, 2021). "In human HCC tumors, expression of SMO positively correlated with tumor size, while an inverse relationship was reported for PTCH1, suggesting overaction of Hh signaling as a result of SMO derepression." (PMID 34572373, 2021). "Increased mRNA levels of Gli1 and Ptch1 were seen in hsBCL9CT-24 or Bcl9-shRNA treated CT26 tumor cells, suggesting that BCL9 suppression activates CD155 expression via sonic hedgehog signaling." (PMID 34417435, 2021).
tumor (continued). "This includes overexpression of HH ligand in tumor and tumor microenvironment (TME), loss of function mutation in PTCH1 and SUFU, GLI2 amplifications, and gain of function mutation in SMO." (PMID 34831357, 2021). "A long non-coding RNA associated with HDAC2 (lncHDAC2) was identified in CD13−/CD133+ cells derived from primary HCC specimens, and was reported to suppress PTCH1 expression and consequently promote self-renewal of tumor-initiating cells through Hh signaling." (PMID 33440657, 2021). "In agreement with this, the analyses performed using the GEPIA tool confirm that in tumor patients the expression of PTCH1 and IGF1 genes is lower than in normal patients, suggesting therefore a downregulation in a more aggressive cell state." (PMID 34157951, 2021). "Expression levels of SMO, GLI1, and PTCH1 as assessed in tumor tissue by real-time quantitative polymerase chain reaction (qPCR) did not predict a response to the addition of vismodegib." (PMID 33498528, 2021). "It was found that TERT‐induced miR500A mediated the down‐regulation of PTCH1, GLI3 and CUL3, while miR500A directly targets the 3′UTR of PTCH1, promoting tumour invasiveness." (PMID 33713376, 2021). "Concerning AKT, it is known that in spontaneous Ptch1+/− tumors only a low percentage of cells (about 20% of tumor mass) are positive for phosphorylated AKT." (PMID 34395258, 2021). "NOTCH inhibition promotes tumor persistence in PTCH1 conditional mice, whereas NOTCH activation is sufficient to induce regression of established lesions." (PMID 33113965, 2020). "The effects of DHA, cisplatin and the combination of cisplatin and DHA on Shh signaling was confirmed by testing the expression levels of nuclear Gli1, PTCH1, and Sox2 in tumor cells obtained from xenografts." (PMID 33363149, 2020). "The results indicated that expression of Shh, Ptch1, Smo and Gli1 protein was upregulated in GC tissues in comparison with adjacent non-tumor tissues." (PMID 32328197, 2020). "For example, analysis of primary esophageal cancers revealed that even though the SHH transcript was localized to the tumor tissue, expression of GLI1 and PTCH1 was found in both the tumor and stroma." (PMID 32957513, 2020). "Mutant U1-mediated aberrant alternative splicing inactivates tumor-suppressor genes (Ptch1, Pax5) and activates oncogenes (Gli2 and Ccnd2) or affects genes linked to SHH pathway (Pax6) or to other tumors (Tox4)." (PMID 32528946, 2020). "In order to evaluate the expression of HH pathway components in canine OSA tumor tissues we performed in situ hybridization for canine Ihh, Smo, Ptch1, Gli1, and Gli2 mRNA on archived, formalin fixed, paraffin-embedded primary canine OSA samples." (PMID 32348319, 2020). "The ISH evaluated cellular gene expression of Ihh, Smo, Ptch1, Gli1, and Gli2 mRNA both in neoplastic cells and stromal cells comprising the tumor microenvironment." (PMID 32348319, 2020). "Taken together, SETDB2 interacts with ΔNp63α, methylates and stabilizes the ΔNp63α protein to upregulate the Hedgehog pathway-associated genes CXCR4, PTCH1 and GLI2, which promote stem cell maintenance, tumor initiation and growth." (PMID 32549764, 2020).
tumor (continued). "In aerodigestive cancer, the combined treatment with SMO and HDAC inhibitors promotes cell cycle arrest, suppresses SMO and PTCH1 expression, and delays tumor growth in an animal model, prolonging survival more than a single agent alone." (PMID 33396427, 2020). "Here, we found that this PTCH1-derived circRNA was significantly up-regulated in tumor tissues and cell lines using microarray analysis and qRT-PCR assays." (PMID 32929380, 2020). "At the molecular level, the transcriptional factor GLI induces several genes involved in tumor progression, and the transmembrane proteins PTCH1 and PTCH2 act as pathway inhibitors." (PMID 33271924, 2020). "Patched 2 (PTCH2) is a second patched member, structurally similar to PTCH1, whose role as a tumour suppressor and response to Hh ligand have yet to be entirely understood." (PMID 31988301, 2020). "Based on panel sequencing results with a PTCH1 loss of function mutation combined with a LOH (variant frequency: 92%) and tumor board decision, vismodegib was initiated in a dose of 150 mg daily in combination with temozolomide." (PMID 32758285, 2020). "Mutations in PTCH1 and CDKN2B were validated using ddPCR in the tumour/normal DNA and the CSF and plasma cfDNA." (PMID 33110059, 2020). "Previous work has shown that CD15 labels Math1 positive, tumour-initiating granule cell precursors within Ptch1 deleted cerebellum, and in combination with CD34, can isolate demarcating neural stem cells and their derived neurons." (PMID 30657775, 2019). "Initial IDHWT tumours also showed predicted pathogenic variation in NOTCH (11%) and SHH (13%) pathways including PTCH1 (PATCHED-1) and SMO (Smoothened)." (PMID 32082376, 2019). "A total of 80% of OKCs are associated with mutations in the gene PTCH1, which are thought to activate a signalling pathway that drives OKC tumour growth." (PMID 30610186, 2019). "In order to further define the pathogenesis of BCCs growth, we developed Ptch1+/−/ODCt/C57BL/6 transgenic mice wherein a single copy loss of Ptch1 causes tumor initiation, and whereupon ornithine decarboxylase (ODC) transgene triggers tumor promotion." (PMID 31506465, 2019). "While overexpression of PTCH1 protein is detected in many kinds of cancer, the function of PTCH1 changes from tumor suppressor to drug transporter for chemotherapeutic agents." (PMID 31704974, 2019). "It is also interesting to consider whether apart from the classical tumor suppressor ‘two-hit’ model, the ‘continuum model’ that accounts for subtle dosage effects, ‘obligate haploinsufficiency’, is associated with the effect of PTCH1 tumor suppressor gene in BCNS." (PMID 30858923, 2019). "IHC staining was undertaken to evaluate the expression of PTCH1 in the tumor tissue and their adjacent histologically normal epithelial cells." (PMID 31554387, 2019). "The mono-allelic exon 15–24 deletion of PTCH1 in Tumor 1 would be predicted to truncate the C-terminal region." (PMID 31362756, 2019).
tumor (continued). "The ability of compound 22 to inhibit tumor cells proliferation and promote cell death was confirmed in Med1-MB cell line generated from a spontaneous tumor arisen in a Ptch1+/−; lacZ mouse." (PMID 31601026, 2019). "In co-cultures, down-regulation of GLI1, SMO, and PTCH1 in the stroma correlated with reduced tumor growth rates in xenografted tumors and cell cultures, confirming a paracrine interaction." (PMID 31658643, 2019). "ERMS tumours from Ptch1+/− mice display high levels of some HH pathway target genes, including Gli1, Ptch1 and Igf2." (PMID 30068568, 2018). "A total of 1095 differentially expressed genes between normal tissues and tumor samples in TCGA data sharing the same MREs as PTCH1 were selected for further study." (PMID 29435142, 2018). "We conclude that like Ptch1, Ptch2 exerts a tumor-suppressive function in BCC cells, and that after targeting of both paralogs, ligand-independent activation of the Hh pathway contributes to tumor growth." (PMID 29869097, 2018). "Even Ptch1 conditional inactivation at later embryonic stage (E14.5–E16.5) leads to rapid tumor formation with 100% medulloblastoma incidence by 3–4 weeks of age in glial fibrillary acid protein (GFAP)-Cre/PtcC/C mice." (PMID 29875630, 2018). "When considering Hh signaling proteins in the epithelium, we observed that low levels of PTCH1 and GLI3 expression were more likely to occur in tumor tissue than in benign (PTCH1 76% PCa versus 26.6% benign, and GLI3 55.2% versus 29%, respectively, p < 0.001)." (PMID 28877722, 2017). "For example, mutations in EGFR and MLL2 were private to 327_T_PDO, whereas tumour 278_T and its models diverged for mutations in FAM123B, MTOR, and for a PTCH1 frameshift mutation predicted to activate oncogenic sonic hedgehog signalling." (PMID 28186126, 2017). "mRNA levels of the Hh target genes Gli1 and Ptch1 were markedly reduced in tumor cells from MGCD0103-treated mice, documenting the inhibition of Hh signaling." (PMID 28276480, 2017). "Immunohistochemical analyses of GLI1, GLI2 and PTCH1 demonstrated that GANT61 was able to specifically inhibit Hh signaling in the tumor." (PMID 28208838, 2017). "Of note, the Hh co-receptor CDON and PTCH1 were expressed in the tumour cells at a level similar to that seen in the stroma, although this did not lead to increased expression of Hh downstream targets in the epithelial compartment." (PMID 27492255, 2016). "To answer this question, we separated RMS tumor tissues and normal gastrocnemius tissues from same Ptch1+/− mouse for IHC staining." (PMID 27999656, 2016). "We obtained fresh TNBC tumor tissues after surgery and analyzed these for the expression of Shh, Patched 1(Ptch1), Smoothened (Smo) and Gli1 at the protein level." (PMID 26727947, 2016). "Using genomic profiling, 10.2% of 186 GIST studied had potentially deleterious genomic alterations in 5 Hedgehog-related genes analyzed, including in the PTCH1 tumor suppressor (1.6%)." (PMID 27793025, 2016). "Similar tumours have been described in a related model, in which Ptch1 was specifically inactivated in a more restricted stromal compartment." (PMID 27492255, 2016). "Surprisingly, other tumor-suppressor genes, such as PTCH1, DAB2IP, and WT1 were included in the gained regions." (PMID 27481518, 2016). "We were able to demonstrate that GANT61 alone or in combination with IR significantly reduced gene expression of the main Hh target genes GLI1, GLI2 and PTCH1 in the tumor cells, but also in the surrounding stroma." (PMID 27713179, 2016). "Mutations in Ptch1 occur in sporadic human MB and promote the tumor in Ptch1 heterozygous mouse models at a rate of approximately 8% within 12 weeks of age and up to 30% between 12 and 25 weeks of age." (PMID 27965576, 2016).